IL34 (interleukin 34)
Diseases named in the same sentence as IL34 in open-access papers (continued):
Sharing a sentence is not in itself a finding about the gene and the disease.
tumor (continued). "Moreover, the secretion of IL-13, IL-34 and osteoactivin by CCA tumor spheres is implicated in the macrophage acquisition of a CSC-specific phenotype characterized by the concomitant expression of M1 and M2 transcription traits and the presence of tumor-promoting functions." (PMID 36612000, 2022). "Seven genes (CACNB2, IL34, CGNL1, CNTN3, GAS7, HOPX, and PBX1) regulated by miR-31-5p and miR-31-3p were identified as putative tumor suppressors." (PMID 34201353, 2021). "Furthermore, to determine whether IL-34 was an independent prognostic marker for GC, we performed univariate and multivariate Cox regression analysis, including IL-34, age, gender, tumour differentiation, lymph node invasion, tumour size, the depth of tumour invasion and TNM stage." (PMID 32765828, 2020). "Univariate analysis revealed that the expression of IL-34, advanced TNM stage, lymph node metastasis, the depth of tumour invasion and tumour diameter were correlated with the prognosis of GC patients." (PMID 32765828, 2020). "While the IL-34/M-CSF/M-CSFR axis is very important for regulating macrophage differentiation, the specific interplay between these cytokines, macrophages and tumour development is unclear." (PMID 32765828, 2020). "In fact, IL-34 expressed by osteosarcoma cells, is regulated by IL-1β and TNF-α, can also recruit macrophages into tumor tissues." (PMID 33224886, 2020). "The MC38 tumor cell line expresses high levels of both cytokines, CSF1 (~900 pg/ml) and IL34 (~300 pg/ml), and thus was utilized to assess macrophage and immune homeostasis in vivo." (PMID 31552020, 2019). "IL‐34 protein expression in HBV‐negative HCC, HBV‐negative adjacent tissues, HBV‐positive tumour tissues and HBV‐positive adjacent tissues were examined." (PMID 31621133, 2019). "We utilized the MC38 tumor model to study how systemic inhibition of CSF1 and/or IL34 impacts the tumor microenvironment and growth." (PMID 31552020, 2019). "After transfected with IL‐34 shRNA, the ability of Huh7‐HBX cells form tumours was significantly lower than that of Huh7‐HBX cells transfected with control plasmids in nude mice." (PMID 31621133, 2019). "Several mouse tumor cell lines were screened for CSF1 and IL34 secretion in vitro in order to identify a relevant cell used for tumorigenesis and to test CSF1R ligand blockade in vivo." (PMID 31552020, 2019). "Patient tissues were stained with antibodies against CD68 for macrophages, pan-cytokeratin for epithelial tumor cells, and with either CSF1 or IL-34." (PMID 29719257, 2018). "Co-localization indicated that pancreatic epithelial tumor cells produce both CSF1 and IL-34 in mouse and human." (PMID 29719257, 2018). "Among the known receptors of IL34, Csf1r was predominantly expressed in the immune cluster, indicating that the IL34-CSF1R axis could be responsible for the regulation of the tumor immune microenvironment." (PMID 40538439, 2025). "In mice, single-nucleus RNA sequencing and phenotyping reveal that the IL34-enriched tumor microenvironment displays immunosuppression and nonfunctional vasculature, two key features of therapy resistance." (PMID 40538439, 2025). "In vitro cell proliferation assays via crystal violet staining revealed that secreted IL34 did not affect the proliferation of Renca cells, ruling out an autocrine mechanism for tumor progression." (PMID 40538439, 2025). "The lungs of mice that did not survive tumor resection were also collected to gain insights into the early steps of the lung metastatic process (i.e., EarlyLM_Ctrl and EarlyLM_IL34-OE)." (PMID 40538439, 2025). "In our previous work, we identified IL34 as a potential biomarker of RCC progression, as its expression was gradually upregulated in serially implanted Renca cells in a cell passage-dependent manner and was concomitant with an increase in tumor aggressiveness." (PMID 40538439, 2025).
tumor (continued). "To determine if IL-34 combined with AFP could improve the specificity in determining HCC, i.e., tumor size, we compared IL-34 versus tumor size, AFP vs tumor size or IL 34 + AFP versus tumor size." (PMID 35347503, 2023). "Intercellular interaction analysis suggested that MFAP5 + fibroblasts could reciprocally communicate with C1QC + macrophages and other myeloid cells to remodel unfavorable conditions via MIF/CD74, IL34/CSF1R, and other tumor-promoting signaling pathways." (PMID 37344903, 2023). "Importantly, analysis of the immune cells infiltrating the tumor showed that combination therapy with PTX and IL-34 blocker was superior to PTX monotherapy in reducing the fraction of M-MDSCs and increasing the number of T cells." (PMID 36765929, 2023). "Furthermore, circulating IL-34 was suppressed with anti-tumor TACE treatment in HBV-HCC, further confirming the potential role of IL-34 during the development of HBV-HCC." (PMID 35347503, 2023). "Furthermore, to investigate the impact of IL34 expression on HCC tumorigenesis, we collected tumor and lung tissues from the mouse model and recorded the volume and weight of the tumors." (PMID 38081923, 2023). "For example, in ongoing clinical trials targeting CSF-1, anti-CSF-1R monoclonal antibodies (such as IMC-CS4 in NCT01346358) block the binding of CSF-1 and IL-34 to CSF-1R and abrogate the recruitment and survival of TAMs, leading to TAM apoptosis and inhibition of tumor growth." (PMID 34683963, 2021). "The expression of IL-34 was up-regulated in serum and tissue samples of PTC, and the overexpression of IL-34 was significantly correlated with distant metastasis and lymphatic metastasis of tumor." (PMID 34930256, 2021). "IL-34 promotes the secretion of pro-inflammatory cytokines and stimulates NF-κB and JNK-related signaling pathways; hence, we wanted to explore the relationship between IL-34 and tumor immune cell infiltration." (PMID 34336646, 2021). "This indicates that IL-34 might be considered as a potential taget for developing new treatments for reducing TAM and tumor proliferation." (PMID 33408768, 2021). "While the IL-34/M-CSF/MCSFR axis is very important for regulating macrophage differentiation, the specific interplay between these cytokines, macrophages and the development of tumours is unclear." (PMID 32765828, 2020). "Furthermore, the role of IL-34 in tumours is controversial particularly in the development, metastasis and prognosis of cancers, although the response to MCSF is tumour-type dependant, possibly due to the levels of M-CSF receptors." (PMID 32765828, 2020). "Tumours with high IL-34 plus high CD68+-TAMs had the best prognosis, tumours with high or low IL-34 plus low or high CD68+-TAMs had mid-level prognosis and tumours with low IL-34 plus low CD68+-TAMs had the worst prognosis in GC patients." (PMID 32765828, 2020). "Consistent with the in vitro findings, Il34 expression in Il34WT, but not in Il34OE, HM-1 tumor was remarkably reduced by the JQ1 treatment." (PMID 33072227, 2020). "By using different molecular techniques, we have recently shown that tumor areas of patients with sporadic CRC contain elevated levels of IL-34 and M-CSF1-R compared to nontumor areas of the same CRC patients and normal controls." (PMID 31968663, 2020). "In addition, we found that IL‐34 is remarkably increased in the serum of patients with PTC and that the levels are closely related to pathological characteristics including tumor size and TNM stage." (PMID 32573824, 2020). "Nevertheless, additional studies are needed to understand macrophage heterogeneity and function within the tumor microenvironment as well as how selective blockade of CSF1, IL34, or CSF1R and subsequent effects on TAMs correspond with response to checkpoint blockade." (PMID 31552020, 2019).
tumor (continued). "This contrasts sharply with the weak or absent correlation between tumor-infiltrating myeloid cells and expression of IL-34, PTPRZ1, and syndecan-1." (PMID 29796177, 2018). "Tumoral samples expressed higher IL-34 RNA levels than non-tumoral samples of the same CRC patients." (PMID 29423057, 2018). "However, no intergroup differences were observed in IL34 levels in the blood, indicating that IL34 secretion by BI PitNETs is confined to the tumor microenvironment, where the excessively secreted IL-34 can act on TNF-α+ TAMs." (PMID 39865310, 2025). "Both IL-34 and CSF1, which are ligands for CSF1R, are known chemotactic factors for circulating monocytes secreted by SCs, and previous work has shown that both IL-34 and CSF1 are expressed in VSs, with a weak correlation between tumor growth and CSF1 levels described." (PMID 38216553, 2024). "To further validate the involvement of IL34+CAFs in promoting Tregs infiltration and impacting tumor growth and metastasis of CD8+ T cells, we utilized lentiviral-mediated overexpression of IL34 in CAFs and mixed them with mouse tumor cells to establish a mouse model of HCC." (PMID 38081923, 2023). "However, there is a lack of research elucidating the spatial distribution of IL34+ CAFs in the tumor microenvironment of HCC, as well as their gene expression characteristics." (PMID 38081923, 2023). "Accumulating evidence supports the view that IL-34-driven activation of MCSF-1R in different cell types present in the CRC mass triggers signalling pathways that sustain either directly or indirectly CRC cell growth, survival and diffusion as well as resistance to anti-tumor therapeutics." (PMID 35837402, 2022). "Since M-CSF and IL-34 bind competitively to the same region of the M-CSFR, this functional difference is not attributable to the need for individually optimised CAR spacer domains, as is required for epitopes that sit at different distances from the tumour cell membrane." (PMID 35883636, 2022). "Notably, strong IL‐34‐positive signals were seen in embryonal tumor cells, but no or weak signals were detected in fetal tumor cells." (PMID 35132816, 2022). "Our findings also indicate that IL-34 is being produced by PDAC CTC in the portal blood and may have a profound effect on skewing myeloid differentiation toward immunosuppression and maintenance of anergy in tumor-directed T cells." (PMID 35316296, 2022). "Moreover, high expression of IL-34 RNA and protein was found in tumour samples of patients with sporadic CRC as compared to non-tumour samples of the same CRC patients and normal controls." (PMID 34535634, 2021). "The results of subgroup analysis further showed that loss of IL-34 expression was related to poor prognosis for LUAD patients who were older than 65 (P = 0.006), male (P = 0.004), in stage III (P = 0.007), with tumor diameter T3 (P = 0.036), or M0 (No distant metastasis, P = 0.005)." (PMID 34336646, 2021). "Indeed, stimulation of both TICs and LPMCs with IL-34 enhanced the expression of CD163 and CD206, typical markers of type 2 macrophages, a subset of cells that play critical roles in the promotion of tumor development, progression, metastasis, and therapeutic resistance." (PMID 33298879, 2020). "Thus, due to limited size of the tumour sample within the array, we are not able to demonstrate the expression of CD68+-TAMs and the loss of IL-34/M-CSF at the interface of tumour invasion region in the existing immunohistochemically stained slides." (PMID 32765828, 2020). "However, in a myeloid cell-rich tumor model, CSF1 but not IL34 was required for tumor-associated macrophage accumulation and immune homeostasis." (PMID 31552020, 2019). "This study was undertaken to assess whether BRD4 controls IL-34 expression in IBD because there is evidence that both these proteins are up-regulated in the inflamed intestine of IBD patients, and studies in tumor cells have shown the ability of BRD4 to positively regulate IL-34 expression." (PMID 39451216, 2024).
tumor (continued). "Thus, HCC cells from the large size tumor may not function properly, and consequently didn’t produce IL-34 as high as small tumor size patients correspondingly." (PMID 35347503, 2023). "Thus, surgical resection of HCC tumor may not have major impact on IL-34 production, compared to the HCC patients had TACE." (PMID 36438052, 2022). "In contrast to the lack of anti-tumor effect of IL-34 or MCSF-1R inhibitor alone, it seems that each of these compounds may enhance the effect of immunotherapy of chemotherapy, thus suggesting a promising opportunity for therapeutic intervention in patients with CRC." (PMID 35837402, 2022). "Similarly, alternative activation of CSF1R by IL34 did not affect tumor cell viability." (PMID 34067348, 2021). "However, it has not been known whether the anti-tumor effect of JQ1 was mediated by IL-34 suppression." (PMID 33072227, 2020). "When cytokine production data were pooled for all six tumour cell lines, significantly greater IFN-γ and IL-2 production was observed for both 2G and 3G CARs in which M-CSF rather than IL-34 was used to confer specificity." (PMID 35883636, 2022). "Our explanation of the correlation among IL-34, TAMs and small tumor size of HCC, but not large tumor size, is such: IL-34 is highly produced by HCC cells from the small size HCC, supporting our finding that high IL-34 was detected in the liver from HCC, as well as from the circulation." (PMID 35347503, 2023). "In summary, TAM homeostasis within the MC38 tumor microenvironment is maintained by production of CSF1, not IL34, and inhibition of signaling not only influenced the myeloid compartment but also inhibited CD4+ T cell accumulation, favoring a reduction in CD4+ FoxP3+ T cells." (PMID 31552020, 2019).
cancer (66 papers, 2015 to 2026). A tumor composed of atypical neoplastic, often pleomorphic cells that invade other tissues. "While less is known about IL-34, except that it can increase monocyte activity, IL-32 has been implicated in fibrosis and cancers associated with chronic inflammation, including HCC39,40." (PMID 38429349, 2024). "It has been also demonstrated that IL-34-stimulated macrophages promoted differentiation of CCR4+ CCR6+ CD161+ Th17 cells and IL-34 expression associated with increased infiltration and function of M2 in various cancers." (PMID 35837402, 2022). "For example, overexpression of CSF1 in breast, prostate, pancreatic, hepatocellular and colorectal cancers, and IL-34 expression in hepatocellular carcinoma, lung and colorectal cancers are associated with disease progression and unfavorable prognosis." (PMID 34803925, 2021). "By immunohistochemistry, we also reported that IL-34 was essentially produced by cancer cells and, to a lesser extent, by CRC-associated immune cells." (PMID 31968663, 2020). "It should be noted that the association between the expression of IL-34 and prognosis varies in different types of cancer, even in the same type of cancer from different databases." (PMID 25395235, 2015). "By performing a search of the COSMIC database, we identified 18 somatic mutations of the IL-34 gene in cancer." (PMID 25395235, 2015). "It was found that the association between the expression of IL-34 and cancer prognosis varied in different types of cancer, even in the same types of cancer from different databases." (PMID 25395235, 2015). "Moreover, IL-34 expression was more pronounced in fibroblasts isolated from ulcerative colitis-associated cancer as compared to normal fibroblasts." (PMID 33260828, 2020). "Such resistance may be caused by the production of CSF-1 and IL-34 not only by aggressive carcinoma cells but also by the brain parenchyma itself." (PMID 26098772, 2015). "Moreover, we identified 18 somatic mutations of IL-34 in cancer tissue in the present study." (PMID 25395235, 2015). "Here, using a validated mouse model for preclinical studies of RCC, the upregulation of IL34 in cancer cells led to the accumulation of monocyte-derived TAMs through CSF1R." (PMID 40538439, 2025). "The levels of CSF1, the other ligand of CSF1R, remained unchanged in IL34-OE cancer cells, indicating that the increase in MD-TAMs was a direct consequence of an IL34-enriched TME." (PMID 40538439, 2025). "Although several studies reported the role of IL34 in cancer, we are still missing therapeutic strategies that target IL34-driven mechanisms to implement in the clinics." (PMID 40538439, 2025). "In colorectal cancer (CRC), cancer cells secrete IL-34 and express CSF-1R, suggesting the presence of an autocrine positive feedback loop on the receptor." (PMID 38254773, 2024). "In some cancers, IL-34 production can be further increased by chemotherapies, and this is particularly evident in those patients who are, or become, resistant to chemotherapy and/or immunotherapy." (PMID 36765929, 2023). "The combination of IL-34 inhibition with ICIs has been proposed as a potential treatment option for cancer due to the role of IL-34 in the TME and its potential involvement in resistance to ICIs." (PMID 36798830, 2023). "Existing evidence suggests that IL-34 is involved in viral infections, autoimmune diseases, and cancer development." (PMID 38081923, 2023). "In this article, we review the current data supporting the role of IL-34 in the differentiation/function of immune suppressive cells and, hence, in the mechanisms leading to therapeutic resistance in various cancers." (PMID 36765929, 2023). "This is in line with experimentation in mouse models of tumorigenesis showing a key role of IL-34 in promoting cancer metastasis." (PMID 36765929, 2023). "Accumulating evidence demonstrated that IL-34 favors the differentiation of M2-phenotype macrophages in diverse cancers by binding to CSF1R." (PMID 37344903, 2023).